TNKS2 (tankyrase 2)
Description:
Poly-ADP-ribosyltransferase involved in various processes such as Wnt signaling pathway, telomere length and vesicle trafficking. Acts as an activator of the Wnt signaling pathway by mediating poly-ADP-ribosylation of AXIN1 and AXIN2, 2 key components of the beta-catenin destruction complex: poly-ADP-ribosylated target proteins are recognized by RNF146, which mediates their ubiquitination and subsequent degradation. Also mediates poly-ADP-ribosylation of BLZF1 and CASC3, followed by recruitment of RNF146 and subsequent ubiquitination. Mediates poly-ADP-ribosylation of TERF1, thereby contributing to the regulation of telomere length. Stimulates 26S proteasome activity.
Synonyms: ARTD6; TANK2; PARP5B; TNKL; PARP-5b; PARP-5c; PARP5C; pART6
Tractability: Small molecule: a drug acting on it is in phase 2 or 3 trials; a structure with a bound ligand is known; a high-quality ligand is known; it has a binding pocket of medium quality; it belongs to a druggable protein family. Antibody: UniProt places it where antibodies can reach, with medium confidence. PROTAC: UniProt records ubiquitination sites on it; ubiquitination databases record sites on it; a small molecule that binds it is known.
Target class: Enzyme; Transferase
Chemical probes: AZ6102 (high quality), E7449 (high quality), JW55, PD134172, XAV939
Gene: Protein-coding gene on chromosome 10 (91,798,426 to 91,865,475, forward strand). Ensembl gene ENSG00000107854.
Subcellular location: Cytoplasm; Golgi apparatus membrane; Nucleus; Chromosome, telomere
Subcellular location (Human Protein Atlas): Microtubules
Pathways (Reactome):
Signal Transduction: Degradation of AXIN; Regulation of PTEN stability and activity; TCF dependent signaling in response to WNT
Disease: XAV939 stabilizes AXIN
Metabolism of proteins: Ub-specific processing proteases
Gene Ontology:
Molecular function: enzyme binding; NAD+ poly-ADP-ribosyltransferase activity; NAD+-protein mono-ADP-ribosyltransferase activity; protein binding; NAD+-protein-aspartate ADP-ribosyltransferase activity; NAD+-protein-glutamate ADP-ribosyltransferase activity
Biological process: negative regulation of telomere maintenance via telomere lengthening; positive regulation of canonical Wnt signaling pathway; positive regulation of telomere capping; protein auto-ADP-ribosylation; protein localization to chromosome, telomeric region; protein poly-ADP-ribosylation; protein polyubiquitination; positive regulation of telomere maintenance via telomerase
Cellular component: cytoplasm; nuclear envelope; nucleus; pericentriolar material; perinuclear region of cytoplasm; chromosome, telomeric region; cytosol; Golgi membrane
Genetic constraint (gnomAD): Loss-of-function variants: 52 observed, 91.93 expected, observed/expected ratio (o/e) 0.57, 90% interval 0.45 to 0.71. The upper end of that interval is the gene's LOEUF score, 0.71, which puts it in group 2 of 6, group 1 being the genes least tolerant of losing a copy. Missense variants: 886 observed, 1,164.9 expected, observed/expected ratio (o/e) 0.76, 90% interval 0.72 to 0.8. Synonymous variants: 454 observed, 430.83 expected, observed/expected ratio (o/e) 1.05, 90% interval 0.98 to 1.14.
Homologues: Orthologues: chimpanzee TNKS2 (100% identical), pig TNKS2 (99% identical), rabbit TNKS2 (99% identical), guinea pig TNKS2 (97% identical), mouse Tnks2 (97% identical), rat Tnks2 (97% identical), dog TNKS2 (95% identical), macaque TNKS2 (95% identical), tropical clawed frog tnks2 (89% identical), Drosophila melanogaster Tnks (65% identical), Caenorhabditis elegans tnsl-1 (19% identical). Paralogues in human: TNKS (81% identical), ANKRD45 (6% identical).